PLAU (plasminogen activator, urokinase)
Diseases named in the same sentence as PLAU in open-access papers (continued):
Sharing a sentence is not in itself a finding about the gene and the disease.
glioma (continued). "With regard to the survival analysis, there is high mRNA level of PLAU/PLAUR in primary and recurrent gliomas as a whole." (PMID 35087738, 2021). "Cox regression analysis indicated that high expression of PLAU and PLAUR were independent prognostic factors for shorter overall survival in glioma patients." (PMID 35087738, 2021). "Using qRT-PCR, we confirmed that the expression levels of FOXM1, PLAU, CYR61, THBS1 and ADAM9 are indeed significantly down-regulated upon HMGA2 depletion in TPC1115 GICs, U87MG glioma cells and SK-N-SH neuroblastoma cells." (PMID 27259253, 2016). "The results showed that TRIM38, CCR5, PLAU, P2RY8, and PROS1 have a higher immunoreaction score (IRS) in tumors than normal tissues (p < 0.05), while the IRS of HAMP and S100A9 in gliomas were lower than normal tissues (p < 0.05)." (PMID 34954691, 2021). "In conclusion, PLAU and PLAUR could be promising prognostic biomarkers and potential therapeutic targets of glioma patients." (PMID 35087738, 2021). "Inhibition of expression of PLAU/PLAUR might blockade these crucial cancer-related pathways, and plays an anti-tumor role in gliomas." (PMID 35087738, 2021). "It is also indicated in the previous research that PLAU mediates regulatory T cells suppressor function through STAT5 and ERK signaling pathways, whereas regulatory T cells participates in complicated immunoreaction in glioma microenvironment." (PMID 35087738, 2021). "However, high expression of PLAU and PLAUR indicated shorter OS in patients with current gliomas of WHO grade III (p=0.0041, p=0.00079 respectively)." (PMID 35087738, 2021). "First, though some recurrent gliomas are found with high expression of PLAU and PLAUR that predict poor prognosis, it is unknown whether the two genes are involved in the recurrence of glioma." (PMID 35087738, 2021). "Among them, PLAU, a serine protease involved in degradation of the extracellular matrix and tumor cell migration and proliferation, might mediate migration and invasion of U87MG glioma cells." (PMID 27259253, 2016). "Similarly, PLAU is highly expressed in GBM specimens, and its expression level is positively correlated with HMGA2 expression in GBM specimens and inversely correlated with glioma patients' survival period." (PMID 27259253, 2016). "The expressions of PLAU and PLAUR were evidently higher in higher WHO grade, recurrent gliomas, wild type IDH-1 and non-codeletion of 1p19q than their counterparts (p<0.0001)." (PMID 35087738, 2021).
COVID-19 (13 papers, 2021 to 2024). A disease caused by infection with severe acute respiratory syndrome coronavirus 2. "The univariate Cox analysis highlighted that 7 genes (including MRC1, CP, ITGA5, SNCA, HARS1, ENPP1, and PLAU) were significantly (p < 0.05) associated with CHOL/COVID-19." (PMID 34176789, 2021). "However, according to scRNA-seq data, PLAU expression increased only in certain cell types (KRT17+ KRT5-) in COVID-19 patients; uPA protein accumulation may be linked to abnormal internalization and lysosomal degradation, directed by uPAR." (PMID 36674896, 2023). "Thus, COVID-19 patients with loss of functions in the PLAU gene may be more likely to develop a thrombotic event." (PMID 35725860, 2022). "In COVID-19 and PF patients, the expression of PLAU and PLAUR in these cells was significantly decreased as compared to the control (p < 0.0001 vs. control)." (PMID 36674896, 2023). "Overall, PLAU expression was low in all monocytes/macrophages in control and COVID-19 samples, but in PF, several AM2, MoM1 and MoM3 cells expressed PLAU." (PMID 36674896, 2023). "In a study of time-order transcriptomics to characterize molecular mechanisms which underpin multiple organ dysfunction in COVID-19, PLAU (plasminogen activator, urokinase) was among the genes to induce olfactory and neurological dysfunction." (PMID 36510222, 2022). "In general, FCER1g, ICAM1, LAT, LCN2, and PLAU may be the main immune genes that are regulated by COVID-19 to induce olf and neurological dysfunction." (PMID 34504502, 2021). "Among all epithelial cells, only airway basal cells were detected to persistently express PLAU and PLAUR, and their expression was significantly decreased in COVID-19 and PF patients." (PMID 36674896, 2023). "PLAU and PLAUR expression was also observed in a fraction of cells from a pro-fibrogenic KRT17+ KRT5- population in COVID-19 and PF patients, though the overall number of PLAU+ and PLAUR+ cells in this population was still low (median normalized expression 0)." (PMID 36674896, 2023). "Molecular docking studies further supported these findings by identifying potential anti-UCEC/COVID-19 pharmacological biotargets of PLB, such as mitogen-activated protein kinase 3 (MAPK3), urokinase-type plasminogen activator (PLAU), and tumour necrosis factor (TNF)." (PMID 39275349, 2024). "Based on the biological molecular docking method, the anti-COVID-19/UCEC effect of PLB could be achieved by some of the core genes, including MAPK3, TNF, and PLAU, as PLB exerted better active cavities and binding affinity in MAPK3, TNF, and PLAU when docking." (PMID 34712201, 2021). "Following molecular docking analysis, in silico investigation helped identify the anti-UCEC/COVID-19 pharmacological bio targets of PLB, including mitogen-activated protein kinase 3 (MAPK3), tumor necrosis factor (TNF), and urokinase-type plasminogen activator (PLAU)." (PMID 34712201, 2021). "As per the independent prognostic and survival analyses, few of the important differentially expressed genes, including MRC1, CP, ITGA5, SNCA, HARS1, ENPP1, and PLAU may function as potent biomarkers for screening and characterizing different stages of CHOL patients with COVID-19." (PMID 34176789, 2021).
hepatocellular carcinoma (13 papers, 2013 to 2026). A malignant tumor that arises from hepatocytes. "As a result, combinations of CDH3, LFNG, and PLAU were significantly associated with overall survival (log-rank test p-value: 2.376 × 10−5) compared to other protein combinations and cancers (e.g. hepatocellular carcinoma, colorectal adenocarcinoma, and lung adenocarcinoma)." (PMID 27869176, 2016). "Our previous studies have shown that miR-193a-3p is involved in multi-drug resistance in both hepatocellular carcinoma and bladder cancer via the repression of different target genes, including SRSF2, PLAU, HIC2 and LOXL4." (PMID 27056900, 2016).
ovarian cancer (13 papers, 2012 to 2024). A primary or metastatic malignant neoplasm involving the ovary. "Ovarian cancer patients, especially those in the advanced stage, often exhibit increased serum levels of PLAU and PLAUR, but while its elevated level is linked to shorter progression-free and overall survival, it does not represent a standalone prognostic indicator." (PMID 38031074, 2023). "VEGFA, PLAU, MMP2, MMP9, and MMP14 expression levels were reduced by stigmasterol treatment, which exerted a complex anticancer effect in the context of ovarian cancer." (PMID 35379271, 2022). "In this module, 5 genes (FN1, MMP2, MMP1, PLAU, and SPARC), colored in green, were identified as ovarian cancer-related genes in the DDOC database." (PMID 25611546, 2015).
cervical carcinoma (8 papers, 2013 to 2025). A carcinoma arising from either the exocervical squamous epithelium or the endocervical glandular epithelium. "Both FN1 and PLAU play pivotal roles in extracellular matrix degradation, facilitating the migration and invasion of cervical cancer cells." (PMID 40141137, 2025). "Specifically, the genes ABL1, BAX, FASN, and PLAU exhibited abnormally high expression levels in cervical cancer specimens, in stark contrast to BCL2, IGF1, and NTRK3, which were markedly under-expressed." (PMID 38988712, 2024). "Additionally, concurrent research has highlighted the pronounced upregulation of PLAU in cervical carcinoma cells." (PMID 38988712, 2024). "However, inhibition of PLAU expression has been shown to prevent the migration and invasion of cervical cancer cells through the downregulation of MMP2." (PMID 34702271, 2021). "Notably, immunohistochemistry and western blot assays confirmed that FN1, PLAU, and ICAM1 are significantly upregulated in cervical cancer tissues." (PMID 40141137, 2025).
head and neck squamous cell carcinoma (8 papers, 2019 to 2025). A squamous cell carcinoma that arises from any of the following anatomic sites: lip and oral cavity, nasal cavity, paranasal sinuses, pharynx, larynx, and salivary glands. "Research in head and neck squamous cell carcinoma (HNSCC) highlights PLAU’s involvement in cell-matrix adhesion, tissue migration, and extracellular matrix binding, facilitating the epithelial stromal transformation (EMT) process and affecting prognosis." (PMID 37889539, 2023).
breast tumor (7 papers, 2001 to 2022). "The versatility of the CRISPR-dCas9 platform to upregulate PLAU expression in cells expressing low levels, while repressing expression in PLAU overexpressing cells, strengthened our conclusion on the oncogenic function of PLAU and its involvement in breast tumor aggressiveness." (PMID 36672610, 2022). "The blockade of TIM-3 in breast tumor explants downregulated genes related to cancer pathways, including those associated with tumor cell proliferation/migration/invasion (WNT5A, LIF, XDH2, SNAI, CDH2, ADAMST12, PLAU, and CDK14)." (PMID 32616706, 2020). "Next, the prognostic value of FN1, PLAU and ALCAM was evaluated in a microarray data set of breast tumors from 2878 patients." (PMID 34641959, 2021). "Our data suggest that BD specifically targets expression of PLAU and CXCR4 in triple-negative and highly aggressive breast tumors in vivo." (PMID 22842551, 2012). "To evaluate the effect of BD on the expression of PLAU (uPA protein) and CXCR4 genes in breast tumors, we isolated RNA and performed quantitative RT-PCR in control and BD treated mice as described in Materials and methods." (PMID 22842551, 2012). "In agreement with our in vitro study, BD treatment significantly downregulated expression of PLAU (p=0.026) and CXCR4 (p=0.002) in breast tumors." (PMID 22842551, 2012). "Finally, anti-metastatic activity of BD in vivo was further confirmed by the downregulation of expression of PLAU (urokinase plasminogen activator, uPA) and CXCR4 (C-X-C chemokine receptor-4) genes in breast tumors." (PMID 22842551, 2012). "They assessed the expression of AHR both in ERα-positive or ERα-negative human breast tumors and found in ER-positive cells a correlation between AHR expression, metastasis occurrence and related markers (MMP1, MMP2), and plasminogen activator urokinase (PLAU)." (PMID 32722276, 2020).
colon carcinoma (7 papers, 2006 to 2026). "The tumor suppressor DKK3 (RIG) induces apoptosis through mitochondrial pathways in human colon cancer and pro-apoptotic actions of PLAU in tumor cells have also been described." (PMID 23702334, 2013). "Pathway analysis indicates that the over-expressed genes largely populate a dense network involved in cell proliferation and migration, including VEGF-A, PLAU and MET (HGF receptor), which have been implicated in control of cellular invasion and in colon cancer specifically." (PMID 17192196, 2006). "Neurotrophin tyrosine kinase receptor type 2 (NTRK2) and urokinase type plasminogen activator (PLAU) were also included because no reports on methylation of the two genes in colon cancer have been published yet." (PMID 19662090, 2009).
lymph node metastasis (7 papers, 2015 to 2024). "The interaction analysis with lymph node metastasis identified PLAU expression as a significant factor affecting all‐cause mortality only in the population with lymph node metastasis." (PMID 38363001, 2024). "The prediction model including CDKN2A, PLAU, T stage and pathological grade can be used as the best diagnostic model for lymph node metastasis in OSCC." (PMID 33968767, 2021). "Moreover, we found that high expression of PLAU was associated with lymph node metastasis, and the potential mechanism was an immune-related pathway, which means that PLAU gene expression analysis helps predict the prognosis and survival of THCA patients." (PMID 35141223, 2022). "High expression of CDKN2A and PLAU was associated with lymph node metastasis in OSCC." (PMID 33968767, 2021). "We investigated the relationship between PLAU and these factors, such as drinking, smoking, the HPV status, sex, the presence of lymph node metastasis and tumour size, because the expression level of PLAU was also confirmed by an immunoblot analysis." (PMID 38363001, 2024). "The model with the combination of CDKN2A, PLAU, T stage and pathological grade was the best in predicting lymph node metastasis (AUC = 0.807, 95% CI: 0.713-0.881, P=0.0001)." (PMID 33968767, 2021). "constructed a prediction model for nodal metastasis based on molecular panel and clinicopathological factors in 112 cN0 OSCC patients, the model with the combination of CDKN2A, PLAU, T stage and pathological grade was the best in predicting lymph node metastasis (AUC = 0.807)." (PMID 37016465, 2023). "Furthermore, the best diagnostic model for lymph node metastasis, which included CDKN2A, PLAU and other clinicopathologic parameters was analyzed." (PMID 33968767, 2021). "Upregulation of PLAU was correlated with lymph node metastasis and poor prognosis of PC." (PMID 33128857, 2020).
melanoma (7 papers, 2011 to 2023). A malignant, usually aggressive tumor composed of atypical, neoplastic melanocytes. "By qPCR, we validated the upregulation of two genes, INHBB and PLAU, in three additional melanoma cell lines." (PMID 23077590, 2012).
pulmonary fibrosis (7 papers, 2013 to 2024). Chronic progressive interstitial lung disorder characterized by the replacement of the lung tissue by connective tissue, leading to progressive dyspnea, respiratory failure, or right heart failure. "Mutations in the CHRM3, HLA-DRB1, PLAU, and SETD2 genes are closely linked to the pathogenesis of pulmonary fibrosis." (PMID 38575860, 2024). "Genes involved in pulmonary fibrosis processes found to be upregulated in CIPF compared with healthy WHWTs in cluster M1 included FN1, SPP1, CXCL8, and PLAU (encoding plasminogen activator urokinase)." (PMID 33384697, 2020). "We identified four overexpressed genes associated with pulmonary fibrosis processes in CIPF compared with healthy dogs in this cluster including FN1, SPP1, CXCL8, and PLAU." (PMID 33384697, 2020). "These experiments have established that miR-199a-5p is directly or indirectly involved in the regulation of genes previously associated with lung fibrosis: CCL2, a potent mononuclear cell chemoattractant, PLAU, a component of the fibrinolysis system, TGFBRI, the TGFβ receptor type I, MMP3 and CAV2." (PMID 23459460, 2013). "Of note, type 3 fibroblasts exhibited an elevated expression of both PLAU and PLAUR in pulmonary fibrosis, while in mesothelial cells, only PLAUR expression was elevated (p < 0.0001 vs. control)." (PMID 36674896, 2023). "The role of the plasminogen activator urokinase (PLAU gene) in pulmonary fibrosis is not clear." (PMID 33384697, 2020).
atherosclerosis (6 papers, 2018 to 2025). A disease characterized by the build-up of fatty material and calcium deposition in the arterial wall resulting in partial or complete occlusion of the arterial lumen. "Because PLAT and PLAU are also associated with atherosclerosis/thrombotic pathways and JAKinib therapy was associated with MACE, we focused on these transcripts for further analyses." (PMID 40522928, 2025). "Because PLAT and PLAU are also associated with atherosclerosis/thrombotic pathways and JAKinib therapy is associated with MACE, we focused on these PLAT and PLAU transcripts for further analyses." (PMID 39386576, 2025). "PLAU has also been reported to be associated with atherosclerosis plaque formation and AMI: macrophage–specific overexpression of the PLAU gene accelerated atherosclerosis, coronary artery occlusions, and premature death in ApoE−/− mice." (PMID 35795669, 2022). "The 6 ingredients were highly related to arteriosclerotic cardiovascular disease and atherosclerosis and could mainly interact with similar targets, e.g., GSK3B, PDPK1, PLAU, etc., or pathways, e.g., Insulin, VEGF, FoxO, etc, providing the basis for integrating plasma drug concentration." (PMID 32922299, 2020).
bladder cancer (5 papers, 2012 to 2021). "Recently, Chen and colleagues reported that lncRNA DANCR directly interacted with LRPPRC and guided LRPPRC protein to bind and stabilize the mRNAs of CCND1, PLAU, and IL-11, resulting in enhanced proliferation, migration, and invasion of bladder cancer cells." (PMID 34671012, 2021). "PLAU, another gene in the dedifferentiated chondrosarcoma- “biased” signature, was found to be involved in dissemination of bladder cancer lung metastases." (PMID 22448124, 2012). "In bladder cancer cells, stabilization of PLAU mRNA level might also contribute to tumor metastasis." (PMID 34093649, 2021).
esophageal cancer (5 papers, 2021 to 2025). A primary or metastatic malignant neoplasm involving the esophagus. "Our study identified COL3A1, PLAU, and SPP1 as key ECM-associated genes with potential as early diagnostic biomarkers for esophageal cancer." (PMID 41465316, 2025). "We identified COL3A1, PLAU, and SPP1 as early-stage esophageal cancer markers, highlighting the role of these genes in disease progression." (PMID 41465316, 2025). "The expression levels of COL3A1, PLAU, and SPP1 were significantly higher in esophageal cancer patients compared to healthy controls (p < 0.05 for all three genes)." (PMID 41465316, 2025). "Together, these mechanisms suggest that COL3A1, PLAU, and SPP1 not only serve as promising biomarkers for early-stage esophageal cancer but also contribute to the pathophysiology of the disease by facilitating key processes such as migration, invasion, and proliferation." (PMID 41465316, 2025).
esophageal squamous cell carcinoma (5 papers, 2022 to 2024). Esophageal squamous cell carcinoma (ESCC) is a type of esophageal carcinoma (EC) that can affect any part of the esophagus, but is usually located in the upper or middle third. "PLAU also promoted Esophageal squamous cell carcinoma proliferation and colony formation through MAPK pathway, and promoted migration through up-regulation of Slug and MMP9, leading to an increase in fibrosis." (PMID 38575860, 2024). "Moreover, PLAU, as a prognostic marker, was found to promote CAFs conversion and the proliferation and migration of esophageal squamous cell carcinoma via the uPAR/Akt/NF-κB/IL8 pathway." (PMID 37775715, 2023).